ERBB2 (erb-b2 receptor tyrosine kinase 2)
Diseases named in the same sentence as ERBB2 in open-access papers (continued):
Sharing a sentence is not in itself a finding about the gene and the disease.
breast cancer (continued). "On the other hand, when ERBB2 was overexpressed in breast cancer cell lines MDA-MB-231 (ERBB2-negative) and MCF 7 (ERBB2-positive) and autophagy was measured by LC3-II Western blotting, basal and amino acid starvation-induced levels of autophagy were increased by at least 40%, respectively." (PMID 33801244, 2021). "Triple-negative breast cancer (TNBC; estrogen receptor α, progesterone receptor and HER2 (ERBB2)-negative) is the subtype of breast cancers with poorest prognosis due to lack of targeted therapies." (PMID 34381711, 2021). "We therefore tested whether the elevated ER stress induction by Bortezomib could have a synergistic or additive effect with Trastuzumab against ErbB2-overexpressing, low CHIP-expressing, BT474 and SKBR3 breast cancer cells." (PMID 34439093, 2021). "Downregulation of ERBB2 or ATG12 increased cell death induced by chemotherapy drugs in ERBB2-positive breast cancer cells, whereas upregulation of ERBB2 or ATG12 decreased the cell death in ERBB2-negative breast cancer cells." (PMID 33801244, 2021). "Thus, it is likely that in ERBB2-positive and basal-like breast cancers, other drivers than CINSARC genes are prominently leading the metastatic process, while in Luminal A breast cancers estrogen receptor signaling plays a major role." (PMID 33953185, 2021). "Through the preliminary screening of qRT-PCR, we focused on a novel circRNA: circ-ERBB2, which was abnormally high expressed in tumor tissues of patients with HER2-positive breast cancer and was interrelated to Lymph node metastasis and HER2 status in patients." (PMID 34732216, 2021). "The probability of relapse for ErbB2+ breast cancer in I–II stages is 2.7 times higher than for ErbB2 negative types, and the chance of metastasis development is 5.3 times higher." (PMID 34944558, 2021). "Based on histological and genetic alterations, breast cancer is grossly categorized into four major subtypes: estrogen receptor (ER)-negative, including ErbB2+ and triple-negative, and ER-positive (Luminal A and Luminal B)." (PMID 33919420, 2021). "Vice versa, in breast cancer (more than 1200 cases analyzed), we never observed a nuclear expression of ErbB2." (PMID 32591879, 2021). "Moreover, immunohistochemistry studies using breast cancer tissues show that DNAJA3/Tid1 levels are inversely correlated with tumor malignancy and ErbB2 levels through direct interaction with ErbB2 to promote CHIP-mediated proteasomal degradation." (PMID 34948322, 2021). "Here, we aimed to perform such an analysis using publicly available gene expression datasets in basal and in the estrogen-positive/ERBB2 negative chemotherapy treated breast cancer." (PMID 34527184, 2021). "Moreover, studies on adult female mice bearing ErbB2-driven breast tumors have shown that inhibition of cyclin D-CDK kinase activity can trigger tumor cell senescence and prevent the progression of breast cancer." (PMID 34977029, 2021). "The ER positive/ERBB2 negative patients represent 70% of all cases, the ERBB2 positive cases account for 15–20%, and the basal cases denote 15% of all breast cancer cases." (PMID 34527184, 2021). "We used these DCs to help identify novel CD4pos Th epitopes on the rat ErbB2/HER-2 protein and demonstrated a subset of these as effective immunogens in a DC-based therapeutic model of HER-2pos breast cancer in Balb/c mice, where they induced powerful Th1-polarized immune responses." (PMID 34579275, 2021). "We identify recurrent derivative chromosomes derived from chromosomes 11 and 17 in breast cancer samples, with homogeneously staining regions for CCND1 and ERBB2, and double minutes and breakage-fusion-bridge cycles in glioblastoma multiforme and ovarian cancer samples, respectively." (PMID 33927198, 2021). "However, classifying breast cancer as HR+/ERRB2–, ERBB2+/HR– or HR+, and triple-negative is vital for targeted therapeutics." (PMID 33670942, 2021).
breast cancer (continued). "This study was a secondary analysis of data from a subset of 565 women with ER-positive/ERBB2-negative breast cancer who participated in the Stockholm tamoxifen (STO-3) randomized clinical trial." (PMID 34190995, 2021). "Finally, ERBB2 antibody treatment led to reduced expression of ATG12 and autophagy inhibition increasing drug or starvation-induced cell death in ERBB2-positive breast cancer cells." (PMID 33801244, 2021). "It has been reported that hyaluronan–CD44 interactions are capable of stimulating ABCB1 expression and activity through promoting ankyrin–cytoskeleton interactions, Nanog-Stat-3 signalling, ErbB2 signalling and PI3K/AKT-related survival pathways in breast cancer cell lines." (PMID 33801148, 2021). "The findings of the present analysis suggest that tumor size is associated with the long-term risk of distant recurrence independent from other clinically used markers among patients with lymph node–negative, ER-positive/ERBB2-negative breast cancer." (PMID 34190995, 2021). "PTPN9 may contribute to tumor suppression by dephosphorylation and silencing of EGFR, ErbB2, and STAT3 in breast cancer." (PMID 34199293, 2021). "Our WES data also revealed that patients not achieving pCR had significant arm-level CNAs of breast cancer-relevant genes, including ERBB2 amplification." (PMID 35480699, 2021). "The main molecular targets in breast cancer pathogenesis are estrogen receptor alpha (ERα), which is expressed in approximately 75% of invasive breast cancers and human epidermal growth factor receptor 2 (ERBB2/HER2), amplified or overexpressed in approximately 15% of breast cancers." (PMID 34356858, 2021). "The study population included 565 postmenopausal women (mean [SD] age, 62.0 [5.3] years) with a diagnosis of ER-positive/ERBB2-negative breast cancer." (PMID 34190995, 2021). "Generally, our data corroborated that circ-ERBB2 might act as an oncogene in HER2-positive breast cancer development and provide two novel regulatory axes for HER2-positive breast cancer: circ-ERBB2/miR-136-5p/TFAP2C and circ-ERBB2/miR-198/TFAP2C." (PMID 34732216, 2021). "There are three molecular classes of breast cancer: hormone receptor positive/ERBB2 (receptor tyrosine-protein kinase)-negative (HR+/ERBB2−), ERBB2 positive (ERBB2+), and triple-negative." (PMID 34532287, 2021). "To investigate the circ-ERBB2 biological function on HER2-positive breast cancer, we firstly assessed the circ-ERBB2 expressions in HER2-positive breast cancer and HER2-negative breast cancer cell lines." (PMID 34732216, 2021). "ERBB2–/HR– breast cancers are extremely challenging to treat since there are no well-known receptor targets that will slow down the proliferative and metastatic phenotypes of this cancer." (PMID 33670942, 2021). "Triple-negative breast cancer (TNBC) is a particular type of breast cancer defined by the absence of estrogen and progesterone receptor expression as well as the absence of ERBB2 amplification, which accounts for 15% to 20% of breast cancers." (PMID 34422088, 2021). "To determine whether ErbB2 regulates the subcellular localization of DEPTOR, we co-transfected ErbB2 with EGFP-fusions of full-length DEPTOR or its domains into ErbB2-negative breast cancer MDA-MB-231 cells or HEK293 cells." (PMID 33995662, 2021). "FOXP3 expression is not restricted to the lymphocyte lineage, but it is also present in some cancer cells, especially in breast cancer cells, where it has been demonstrated to be a cancer-suppressor gene and an important regulator of the HER2/ErbB2 and SKP2 oncogenes." (PMID 33671179, 2021). "Importantly, our observed correlation between ERBB2 and ESR1 expression patterns and pCR resembles that shown for breast cancer tissues from patients receiving NAC with very similar cut-offs." (PMID 34073233, 2021). "However, in breast cancers with concurrent low HER3 abundance and ERBB2 amplification, HER2 signalling is maintained by homodimerization." (PMID 34771477, 2021).
breast cancer (continued). "Triple-negative breast cancer (TNBC) is a subtype of breast cancer characterized by the absence of estrogen receptor (ER), progesterone receptor (PR) expression, and of epidermal growth factor receptor 2 (ERBB2) gene amplification." (PMID 34649623, 2021). "Our findings from the current study are concordant with our previously published work on transcription factors such as ERBB2, RABL6, FOXM1 and MITF which are most effected by palbociclib treatment in MDA-MB-231 breast cancer cells, reducing colony formation, cell migration and viability." (PMID 34565361, 2021). "To test this hypothesis, we investigated the expression and chromatin-based epigenetic signature of the ERBB2 gene in epithelial-like HER2-high and mesenchymal-like HER2-low breast cancer cells." (PMID 34575017, 2021). "IFNγ and phenformin also cooperatively elicit antitumorigenic responses in murine ErbB2+ (NOP6, NOP23, and NIC) and human breast cancer cell lines representative of ER+/HER2− (MCF7), HER2+ (HCC1954, BT474), and triple-negative (MDA-MB-231, BT20, MDA-MB-436, Hs578T, and BT549) disease." (PMID 34083537, 2021). "In a Europe-wide external quality assessment, we compared performance of an mRNA-based method [Xpert® Breast Cancer STRAT4 (CE-IVD)] for determining ESR1, PGR, ERBB2, and MKI67 expression against the gold standard [immunohistochemistry (IHC)/HER2 in situ hybridization (ISH)]." (PMID 34572945, 2021). "Our results show that PLC presents at more advanced stage than breast cancer not otherwise specified and harbors high percentages of both ERBB2 alterations and PI3K pathway alterations." (PMID 33441174, 2021). "Moreover, gene set enrichment analyses (GSEA) found that genes of cancer proliferation, breast cancer progress, and ERBB2 (HER2) breast tumors were upregulated in ++Oxtr tumors." (PMID 34099636, 2021). "ER positive ERBB2 negative tumors represent the largest cohort of breast cancer patients with over two third of all patients." (PMID 34527184, 2021). "In fact, the analysis of 200 ERBB2-amplified tumors showed that the SRCIN1 gene is often (55–60% of ERBB2-amplified breast cancer patients), but not necessarily co-amplified with ERBB2." (PMID 34708040, 2021). "Hormone receptor‐positive, HER2 (ERBB2)‐negative (HR+HER2−) breast cancer accounts for 70% of all breast cancers." (PMID 33022852, 2020). "Specific post-translational modifications of MZF1 are induced in invasive cancer, as is the case for breast cancer harboring ErbB2 activation, and these are necessary for the invasive signaling mediated via MZF1 in response to ErbB2 activation in breast cancer cells." (PMID 31963147, 2020). "Moreover, a MZF1 target gene AXL, which can be activated upon lapatinib resistance in ErbB2 positive breast cancer cells, has been shown to induce EMT in breast cancer cells." (PMID 31963147, 2020). "ERBB2-enriched breast cancer incidence rates increased in non-Hispanic White women aged 25 to 39 years (APC, 4.7%; 95% CI, 1.5% to 8.0%)." (PMID 32804214, 2020). "Two CSF ctDNA samples had a gain of ERBB2 (HER2) copy number from a parotid carcinoma patient, while an increase in CD44 copy number was identified in three patients, in which each patient has breast cancer, gastric cancer and unknown cancer, respectively." (PMID 32711494, 2020). "Invasive lobular carcinoma (ILC) accounts for 10–15% of primary breast cancers and is typically estrogen receptor alpha positive (ER+) and ERBB2 non-amplified." (PMID 32782013, 2020). "In breast cancer, MET and ERBB2 are also coexpressed and related to therapeutic resistance." (PMID 33204717, 2020). "Both UCC14-PDC (IC50 508.3 nM) and MGHU3 (an ERBB2 wildtype bladder cancer line, IC50 245.9 nM) were significantly less sensitive to neratinib as compared to CVX-437 (a HER2 S310F-mutant cervical cancer line, IC50 56.8 nM) and BT-474 (an ERBB2 amplified breast cancer cell line, IC50 0.1 nM)." (PMID 32332851, 2020).
breast cancer (continued). "ERBB2-enriched breast cancer incidence rates increased for young non-Hispanic White women, while triple-negative breast cancer incidence rates decreased for midlife non-Hispanic White and non-Hispanic Black women." (PMID 32804214, 2020). "Most notably, the amplification of the ERBB2 (HER2) oncogene defines a biological subtype of breast cancers and targeting this CNA has led to the development of a multitude of efficacious therapeutic agents that have dramatically increased the survival of HER2+ patients." (PMID 32401198, 2020). "In particular, in utero BPA exposure to a dose of 500 ng/kg BPA, but not the high dose group, significantly promoted mammary tumor development in the erbB2 mice." (PMID 32353937, 2020). "Incidence rates for ERBB2-enriched breast cancer increased by 4.7% (95% CI, 1.5% to 8.0%) annually for non-Hispanic White women aged 25 to 39 years." (PMID 32804214, 2020). "Triple negative breast cancer is a collection of heterogeneous breast cancers that are immunohistochemically negative for estrogen receptor, progesterone receptor, and ErbB2 (due to deletion or lack of amplification)." (PMID 32349331, 2020). "Furthermore, selatinib offers better security and can be clinically developed to treat gastric cancer, breast cancer, and non-small cell lung cancer, with high expression levels of EGFR and ErbB2." (PMID 32535812, 2020). "Evaluating the same assay on non-TNBC revealed four genes: ERBB2, ESR1, PHGDH, and TYMS containing both germline and somatic mutations significantly associated with that type of breast cancer." (PMID 32724790, 2020). "Chemotherapy is recommended for patients with ERBB2-positive and HR-negative tumors, node-positive disease, and high Oncotype recurrence scores in HR-positive and ERBB2-negative breast cancer." (PMID 32644137, 2020). "Moreover, NECL2 and NECL4 can interact with PTPN13 to inhibit the ERBB2/ERBB3 pathway in colorectal cancer (Caco-2), breast cancer (MCF7), and human embryonic kidney (HEK293) cells." (PMID 33322542, 2020). "Sacituzumab govitecan and pembrolizumab combination is under investigation in hormone receptor-positive and ErbB2-negative advanced breast cancer (NCT04448886), and in advanced TNBC (NCT04468061)." (PMID 33081383, 2020). "We validated the molecular characteristics of this cell line by portraying the expression profiles of ER and ErbB2 and comparing them to those of two other breast cancer cell lines: MCF-7, which corresponds to a luminal subtype, and SKBR3, which corresponds to HER2 (ErbB2)-enriched subgroups." (PMID 32185126, 2020). "ERBB2 is a proto-oncogene, that is present at higher levels in premenopausal women and in estrogen receptor (ER) negative breast cancers than in ER positive breast cancers." (PMID 33331402, 2020). "In order to study the spatial correlation of single ErbB2 proteins and actin filaments, we applied correlative fluorescence microscopy (FM), and scanning transmission electron microscopy (STEM) to image specifically labeled SKBR3 breast cancer cells." (PMID 32714928, 2020). "Of note, add-on metformin to neo-adjuvant treatment of ErbB2 breast cancer in non-diabetic patients has recently been reported to fail in improving pathologic complete response, indicating perhaps metformin limitation in the non-diabetic breast cancer context." (PMID 32695336, 2020). "Consistent with our results, analysis of multiple, publicly available breast cancer mRNA expression datasets also showed significantly higher SRPK1 mRNA expression in TNBC (ERBB2/ER/PR negative) samples compared to non-TNBC breast cancers." (PMID 32859889, 2020). "This cohort study examines the association of overall survival with endocrine therapy to treat hormone receptor–positive, ERBB2-negative breast cancer." (PMID 32833014, 2020).
breast cancer (continued). "The efficacy of add-on metformin in the treatment of ErbB2 breast cancer in non-diabetic patients still remains to be prospectively verified." (PMID 32695336, 2020). "In contrast, hormone receptor–negative tumors (corresponding to both ERBB2-enriched and triple-negative molecular breast cancer subtypes) decreased for women of all racial/ethnic groups by 1.5% to 2.6% per year." (PMID 32804214, 2020). "Downregulation of Notch3 but not Notch1 considerably suppressed proliferation and induced apoptosis of the Erbb2-negative breast cancer cell lines implicating Notch3-mediated signaling in the proliferation of these cells." (PMID 32211044, 2020). "Since a functional and physical association between ERBB2 family members and the RANK receptor has been shown, clinical trials of combinatorial administration of immune checkpoint inhibitors and anti-RANKL agents in breast cancer, especially in RANK-expressing ERBB2-positive patients, are needed." (PMID 33066388, 2020). "The basis was laid in the phase II PALOMA-1/TRIO-18 clinical study in patients with previously untreated, advanced-stage, ER-positive, ErbB2-negative breast cancer." (PMID 33255177, 2020). "Consistent with our results, analysis of multiple publicly available breast cancer mRNA expression datasets also showed significantly higher LIMK2 mRNA expression in TNBC (ERBB2/ER/PR negative) compared to breast cancer with other biomarker status 21–26." (PMID 32859889, 2020). "Breast cancer is categorized into three major subtypes based on the presence or absence of molecular markers for estrogen receptors (ERs), progesterone receptors (PRs), and human epidermal growth factor 2 (ERBB2, formerly HER2/neu)." (PMID 32164337, 2020). "The breast cancer biomarkers ERBB2 (HER2), ESR1(ER), PIK3CA are not significantly altered in patients with BRF2 alterations." (PMID 33176745, 2020). "Mice lacking cyclin D1 were also resistant to breast cancers induced by the erbB-2 and ras oncogenes, but were sensitive to breast cancers induced by other oncogenes like c-myc or Wnt-1." (PMID 31884567, 2020). "The breast cancer cells were grown on microchips, transformed to express an actin-green fluorescent protein (GFP) fusion protein, and labeled with quantum dot (QD) nanoparticles attached to specific anti-ErbB2 Affibodies." (PMID 32714928, 2020). "In breast cancer, transcription factor AP-2 gamma (TFAP2C) is an important transcription factor that regulates estrogen receptor-alpha (ERα) and c-ErbB2/HER2 (Her2), which are involved in the establishment of the gene expression pattern observed in different clinical phenotypes of breast cancer." (PMID 32571353, 2020). "The MONARCH study series enrolled patients with hormone receptor positive, ErbB2-negative advanced breast cancer and led to FDA approval of abemaciclib as initial endocrine-based therapy in combination with an aromatase inhibitor." (PMID 33255177, 2020). "Unlike breast cancer where ERBB2 is frequently amplified and plays an important role in tumor progression, ERBB2 amplification is detected at low frequency in PDAC14." (PMID 32251323, 2020). "Interestingly, we identified a key network centered on ERBB2 (Erb-B2 Receptor Tyrosine Kinase 2), commonly known as HER2, widely recognized as a breast cancer biomarker and a relevant player in gynecologic malignancies." (PMID 33424936, 2020). "This study series enrolled patients with hormone receptor positive, ErbB2-negative advanced breast cancer." (PMID 33255177, 2020). "The FDA approval of palbociclib for treatment of ER-positive, v-erb-b2 avian erythroblastic leukemia viral oncogene homolog 2 (ErbB2)-negative breast cancer patients was a major breakthrough." (PMID 33255177, 2020). "Breast cancer is classified into different molecular subtypes based on expression of hormone receptors (HR): estrogen receptor and/or progesterone receptor and human EGF receptor 2 (HER2), also known as receptor tyrosine-protein kinase erbB-2." (PMID 32369771, 2020).